H19 (H19 imprinted maternally expressed transcript)
Diseases named in the same sentence as H19 in open-access papers (continued):
Sharing a sentence is not in itself a finding about the gene and the disease.
cancer (continued). "As epitalon has been shown to bind to H1 it is possible that peptide may downregulate telomerase in cancer cells (through H1 binding and H19 upregulation), and activate ALT (through protein trapping) at the same time." (PMID 40908429, 2025). "By inhibiting miR-141, H19 promotes cancer stemness and resistance to oxaliplatin." (PMID 40781643, 2025). "Notably, MEG3, MIAT, Malat1, SNHG20, SNHG12, Ftx, Pvt1, Mir9-3hg expression in cancer immune cells was associated with an immunosuppressive phenotype, while H19, SNHG6, Trp53cor1, MiR17hg and MiR142hg were linked to a pro-inflammatory phenotype in cancer." (PMID 40527978, 2025). "Based on these results, H19 may be a promising therapeutic target or biomarker for the diagnosis, prevention, treatment, and prognosis of cancer." (PMID 38355574, 2024). "The long noncoding RNA H19 quantified in fresh breast biopsies might be a possible biomarker for cancer detection and subcategorization of lesions." (PMID 39274207, 2024). "We summarized the molecular mechanisms by which H19 regulates apoptosis and autophagy in the pathogenesis of cancers via its regulatory function in several oncogenic signaling pathways, such as the PI3K/Akt and canonical Wnt/β-catenin pathways, and through the H19/miR-675 axis." (PMID 38355574, 2024). "The EGFR, long noncoding RNA H19, LAMC1, and SNP rs3768617 could also increase the risk of cancer, causing the progression, metastasis, and expression with inflammation and oxidative stress markers of lung, liver, renal cancer, and chronic kidney diseases." (PMID 39682093, 2024). "Increasing evidence suggests that H19 plays a crucial role in various human cancers, including HCC." (PMID 39714087, 2024). "As MALAT1, HOTAIR, and H19 have proven to have roles in cancer progression by regulating proliferation, apoptosis, cell cycle progression, and ROS levels as the main biological functions, these lncRNAs are considered proper targets in the treatment of various malignancies, including AML." (PMID 38777995, 2024). "LncRNAs such as MALAT-1, HULC, and H19 have been implicated in human HCC, RCC, and other cancers; however, the functional contributions of these and other lncRNA genes remain largely unknown." (PMID 39682093, 2024). "Because molecular changes take place before morphological alterations in cancer lesions, the lncRNA H19 might also provide insight into patient prognosis, follow-up, and therapeutical management." (PMID 39274207, 2024). "In this review, we focused on the role of H19 in cancer through the modulation of PCD." (PMID 38355574, 2024). "In addition, a DNA plasmid named H19-DTA (also known as BC-819), which targets the expression of a fragment of the diphtheria toxin (DT-A) under the control of the H19 promoter, provides a feasible novel therapeutic option for H19-targeted cancer therapy." (PMID 38355574, 2024). "Abnormally elevated H19 displays carcinogenic effects by regulating PCDs in cancer cells." (PMID 38355574, 2024). "Silencing of H19 results in cell death and progression arrest in cancers." (PMID 38166752, 2024). "H19 is also well known to trigger chemo- and radio-resistance in cancer cells." (PMID 39403602, 2024). "Overexpression of H19 in cancer cells inhibits PCD by directly targeting the target gene, miR-675." (PMID 38355574, 2024). "H19 can also interact with other genes and molecules to regulate key cancer-related processes." (PMID 38166752, 2024). "H19 is one of the most extensively studied classical lncRNAs due to its crucial roles in both normal developmental processes and pathological conditions such as cancer." (PMID 38166752, 2024). "In this direction, the potential research focus might be on long non-coding RNAs (lncRNAs) like H19, which serve critical biological functions and show significant dysregulation in cancer." (PMID 38317193, 2024). "H19 expression is often dysregulated in various types of cancer." (PMID 38166752, 2024).
cancer (continued). "In addition to inhibiting apoptosis in cancer cells, H19 triggers necroptosis by influencing miR-675 expression." (PMID 38355574, 2024). "LncRNA H19 (H19) was the first lncRNA to function as an oncogene in many malignant tumors." (PMID 38791310, 2024). "H19 also promotes autophagy in cancer cells via the PI3K–Akt–mTOR pathway." (PMID 38355574, 2024). "Given the significance of H19 in malignant diseases, particularly GCs, it would be beneficial to further investigate the molecular pathways involving H19 in GCs and analyze their impact on the advancement and outcome of these cancer subtypes." (PMID 38166752, 2024). "In particular, lncRNA H19, upregulated in a number of human cancers, such as in hepatocellular, bladder, and breast carcinomas, has been implicated in inducing EMT and cancer metastasis." (PMID 37384249, 2023). "H19 acts as an oncogene or a suppressor gene, which may be attributed to the heterogeneity of different types of cancer." (PMID 37480014, 2023). "In addition to these techniques, lncRNAs such as H19, often aberrantly expressed in various cancers including CRC, can be targeted." (PMID 37760852, 2023). "Furthermore, there is a statistical association between SPRY4‐IT1 (p = .03) and H19 (p = .04) expression levels and HER‐2 in cancer patients' blood samples." (PMID 36274054, 2023). "H19 was involved in aerobic glycolysis in cancer cells, according to earlier research." (PMID 37821504, 2023). "These discoveries revealed that Brevilin A curbed the pro-cancer function of lncRNA H19." (PMID 37253635, 2023). "Moreover, the downregulation of H19 expression in postoperative patients was revealed in some types of cancers; hence, the monitoring function of H19 was revealed." (PMID 37189829, 2023). "Such as, lncRNA H19 upregulate the Sox4 in cancer cell via downregulation of miR-138." (PMID 36685962, 2022). "Summary the drug resistance mechanisms to human cancers via H19." (PMID 36246634, 2022). "However, opposite findings were reported in other cancers, including bladder cancer, colon cancer, and gastric cancer, rendering H19 an oncogenic gene." (PMID 35565245, 2022). "However, future investigations should focus on the sensitivity and specificity of MALAT1 and H19 in cancer detection." (PMID 35052495, 2022). "For this reason, clinically, lncRNA H19 could be useful as a biomarker of diagnosis, therapy, and prognosis in cancer." (PMID 35955440, 2022). "H19 has been extensively studied in cancer, endocrine, and cardiovascular diseases." (PMID 36188624, 2022). "Of these, H19 was initially recognized as an oncofetal transcript, and aberrant increase in its expression has been observed in malignant tissues in several types of cancers." (PMID 35166018, 2022). "Moreover, the relation of chromatin-associated RNAs with cancer progression has been documented in many instances, such as PVT1, H19, MALAT1, and HOTAIR (for a recent review, see reference 45)." (PMID 36445136, 2022). "Our results showed that H19 could function as ceRNA by sponging five miRNAs, which may promote the progression of cancer." (PMID 36090894, 2022). "Summary of different resistant drugs to human cancers via H19." (PMID 36246634, 2022). "H19 overexpression has been reported in cancer cell lines and clinical specimens." (PMID 35674441, 2022). "Recently, the lncRNA H19 (H19) has been identified as a cancer promotor in different cancer types." (PMID 35359403, 2022). "Furthermore, the methylation rates of the H19 promoter in EBV-positive cancer cells were reduced following treatment with 5-Aza-CdR." (PMID 35674441, 2022). "Numerous human cancers have been shown to express the lncRNA H19 in large quantities." (PMID 36591473, 2022). "The expression of H19 in lncRNA is altered in various cancer types." (PMID 36139647, 2022). "In addition to H19, other differentially expressed lncRNAs are involved in disease occurrence, cancer invasion, metastasis, EMT, and methylation." (PMID 35571069, 2022).
cancer (continued). "H19 was upregulated in cancer patients compared with controls." (PMID 35656022, 2022). "However, H19 is reactivated in some pathological states, including tissue regeneration, cancer, hypoxia, and CNS disease." (PMID 36364766, 2022). "In colorectal cancer, H19 regulates the stemness of cancer cells with ALDH enzyme activity." (PMID 35954194, 2022). "CUR attenuated H19-induced alterations in N-cadherin and E-cadherin expression levels and inhibited H19-induced invasion and migration, indicating that CUR may prevent H19-associated cancer cell metastasis." (PMID 36552560, 2022). "Moreover, after knocking down the expression of H19, the proliferation, migration, and tube formation of ox-LDL-induced HAECs were significantly inhibited, which is similar to the role of the H19 in many cancer cells." (PMID 35345660, 2022). "The mechanism that dictates H19 behaviour differs between cancer types." (PMID 33669311, 2021). "In addition, CAF-derived exosomal H19 was found to promote oxaliplatin resistance in recipient cancer cells in vitro and in vivo." (PMID 33920605, 2021). "The H19- myoblast presented characteristics similar to cancer cells, therefore the H19 lncRNA may be an important gene during the initiation of the tumorigenic process." (PMID 34526543, 2021). "MRPL23‐AS1 is a non‐coding cancer‐related gene located 5.9 kb downstream of H19 rs2839701." (PMID 33236528, 2021). "In fact, since the discovery of MALAT1 (Metastasis-associated lung adenocarcinoma transcript 1) in the early 2000s, dysregulation of more than a dozen other lncRNAs, such as H19, XIST, and HOTAIR have steadily been found to be associated with cancer progression and drug resistance." (PMID 33803328, 2021). "Several studies have demonstrated that lncRNA H19 could act as a competing endogenous RNA (ceRNA) to sponge miR‐29b‐3p in various cancers." (PMID 33463060, 2021). "H19 has been found to act as a microRNA sponge to indirectly regulate the expression of microRNA downstream target genes thus mediating cancer progression in several cancer types." (PMID 34250088, 2021). "However, H19 is abnormally upregulated in various cancers, including breast, liver, lung, esophageal, pancreatic, ovarian, and bladder." (PMID 34760887, 2021). "Increasing evidence has shown that H19, as an oncogene, induces cancer cell apoptosis." (PMID 34977037, 2021). "Among them, lncRNA H19 has been found to be abnormally expressed in human malignant tumors and regulates cell proliferation, migration, invasion, antiapoptosis, and epithelial-mesenchymal transition (EMT) through various mechanisms, thus playing a carcinogenic or anticancer role." (PMID 34250088, 2021). "Here, H19 was found to act as a competing endogenous RNA (CeRNA) sponge for miR-141, a known inhibitor of cancer cell stemness, and to activate Wnt/β-catenin signaling in recipient cancer cells." (PMID 33920605, 2021). "H19 has been reported to differentially expressed in liver metastases of different cancers." (PMID 34307387, 2021). "Under pathological processes, such as cancer, H19 can be re-expressed." (PMID 34977037, 2021). "This review suggests that H19 may be a novel therapeutic target for cancers treatment by regulating oncogenic signaling pathways." (PMID 34977037, 2021). "Taken together, these findings may enhance our understanding of the potential role of H19 SNPs in cancer pathogenesis and suggest that H19 SNPs may play an important role in the development of both adult and paediatric cancers." (PMID 33236528, 2021). "Studies suggest that exosomal transmission of H19 may be a major regulator of chemoresistance in several cancer types." (PMID 33920605, 2021). "(ii) Accumulating data suggest that H19 is expressed in almost every human cancer, so could H19 lead to unpredictable toxicity and side effects during the process of influencing CH?" (PMID 34344446, 2021).
cancer (continued). "Based on the effect of H19 on drug resistance of individual cancers, H19 regulatory sequence with high or low expression may serve as a potential therapeutic target to reverse or hinder the occurrence of drug resistance." (PMID 33402118, 2021). "Recently, we have shown in multiple cancers that the Pim kinases regulate H19 levels suggesting Pim could play a role in NEtD59." (PMID 34934057, 2021). "LncRNA H19 is a potential novel therapeutic target for amelioration of cancer therapy resistance." (PMID 33402118, 2021). "H19 also participates in the tumorigenesis of several cancers." (PMID 34820419, 2021). "lncRNA H19 is a highly conserved sequence that has been well studied in the field of cancer." (PMID 33463060, 2021). "In conclusion, the detection of lower LINC00152 in exosomes of sera from CRC patients versus non-cancer individuals and H19 upregulation in advanced stages suggests that they may play important roles in pathogenesis and progression of CRC." (PMID 34571795, 2021). "The long noncoding RNA (lncRNA) H19 plays a crucial role in the development of cancer." (PMID 32323721, 2020). "The cancer cell-specific expression of H19 was harnessed to design a DNA therapy approach to selectively kill H19 expressing cancer cells by expressing diphtheria toxin A under the control of the H19 promoter." (PMID 32326624, 2020). "Indeed, H19 sponges miR-200a or miR-200b/c to promote cancer metastasis through ZEB1 and ZEB2 upregulations." (PMID 32610610, 2020). "Furthermore, we analyzed cancer‐related lncRNAs in the data and our analysis revealed that compared to L02 cells, H19 expression was dramatically increased in MHCC97H and HCC‐LM3 cells." (PMID 32485786, 2020). "Interestingly, an imprinting gene, known as H19 imprinted maternally expressed transcript (H19), produces a lncRNA expressed in a variety of cancer cells that works through different mechanisms to affect the progression and development of each cancer." (PMID 32466143, 2020). "LncRNA H19 has a unique expression profile and can act as a sponger of specific miRNAs to regulate the pathogenic process of many diseases, including PDAC and several other types of cancers." (PMID 32272875, 2020). "H19 is a well-known oncogene and acts as a driving force in a variety of cancers." (PMID 32024523, 2020). "Finally, H19 expression was significantly increased in cancer cells treated with chemotherapeutic drugs (e.g., doxorubicin and cisplatin)." (PMID 33519915, 2020). "Collectively, H19 acts as an oncogenic sponger to target specific miRNAs and enhance their targeted protein expression, promoting the progression of different types of cancers." (PMID 32272875, 2020). "However, there was down-regulation of TTTY14 and H19 in cancer tissue in comparison to normal tissue." (PMID 32998396, 2020). "On one hand, H19 is a precursor of miR-675 as well as a “molecular sponge” for soaking up microRNAs let-7 and miR-138, supporting a role in promoting cancer cell proliferation and migration." (PMID 33519915, 2020). "H19 is reportedly involved in cancer progression and tumorigenesis." (PMID 32337223, 2020). "Our results showed that the long noncoding RNA H19 measured in fresh breast biopsies could not only be a potential marker for cancer diagnosis, but also a good marker for subcatecorizing the lesions." (PMID 33335214, 2020). "H19 is widely described to be involved in tumorigenesis and cancer progression." (PMID 33291403, 2020).
cancer (continued). "In most malignancies, H19 plays a role as an oncogene involved in cell proliferation, cell cycle regulation, apoptosis, migration, invasion, and stemness, as well as the promotion of tumorigenesis in different types of cancers 9-12." (PMID 32626524, 2020). "Hypothesizing that molecular changes often occur before morphological variations, the levels of the LncRNA H19 were measured in anonymous tissues obtained from 79 women’s image guided breast biopsies, and correlated with cancer progression and aggressiveness." (PMID 33335214, 2020). "The targeted miRNAs by H19 depend on the origin of the malignant tumors." (PMID 32272875, 2020). "Moreover, the involvement of lncRNA H19 and NEAT1 in HDAC activity has been reported in association with cancer." (PMID 33050646, 2020). "For instance, MALAT1 in lung cancer, H19 in colorectal cancer, HULC in liver cancer, UCA1 in bladder cancer, and PVT1 in renal cancer are the known diagnostic biomarkers in respective cancers and are under investigation for the targeted treatment." (PMID 33281872, 2020). "Since the molecular changes occur way before the morphological changes in cancer lesions, the lncRNA H19 could also provide information on patient prognosis and possibly on patient follow up and treatment." (PMID 33335214, 2020). "Less aggressiveness would be related to cancers showing high H19 expression." (PMID 33335214, 2020). "While tissue-specific changes in H19 expression have been investigated as potential biomarkers in other conditions including breast cancer, this is the first report of H19 expression in cumulus cells, which are easily accessible at the time of oocyte retrieval." (PMID 32404103, 2020). "Intensive cancer studies have regarded H19 as an oncogene, so it might serve as a therapeutic target in cancer treatment." (PMID 33193379, 2020). "A recent study has analyzed the role of H19 in 24-types of cancer." (PMID 33193379, 2020). "In addition, H19 levels were significantly upregulated in both chemotherapy-sensitive and chemotherapy-resistant cancer tissues relative to their adjacent normal tissues." (PMID 32345117, 2020). "Currently, it is unclear why the same H19 targets different miRNAs in different types of cancers." (PMID 32272875, 2020). "In addition, hypoxia induces lncRNA H19 expression, which is involved in hypoxia-induced signal transduction processes in cancer cells, resulting in modulating glucose metabolism." (PMID 32331347, 2020). "According to lnc2Cancer, the most studied cancer-associated lncRNAs are MALAT1, H19, HOX antisense intergenic RNA (HOTAIR), maternally expressed 3 (MEG3), taurine upregulated 1 (TUG1), antisense non-coding RNA in the INK4 locus (ANRIL) and nuclear-enriched abundant transcript 1 (NEAT1)." (PMID 32340118, 2020). "In addition, we found DAMEs corresponding to known regions exhibiting loss of imprinting in cancer, including those in the genes MEG3, H19, and GNAS." (PMID 32487212, 2020). "Furthermore, we focused on the seven lncRNAs (PFKL, TPD52, ERGIC3, CFL1, CARS, IARS, and H19), which were related to cancer development." (PMID 32485786, 2020). "H19 is related to many important miRNAs in the network of cancer-related functions." (PMID 33330574, 2020). "H19 involvement in various cancers has been well documented." (PMID 32699525, 2020).